ZNF543 (zinc finger protein 543)
Description:
May be involved in transcriptional regulation.
Synonyms: DKFZp434H055
Tractability: PROTAC: ubiquitination databases record sites on it.
Gene: Protein-coding gene on chromosome 19 (57,320,472 to 57,330,770, forward strand). Ensembl gene ENSG00000178229.
Subcellular location: Nucleus
Subcellular location (Human Protein Atlas): Nucleoplasm
Pathways (Reactome):
Gene expression (Transcription): Generic Transcription Pathway
Gene Ontology:
Molecular function: protein binding; DNA-binding transcription factor activity, RNA polymerase II-specific; RNA polymerase II cis-regulatory region sequence-specific DNA binding
Biological process: regulation of transcription by RNA polymerase II; regulation of DNA-templated transcription
Cellular component: nucleus
Genetic constraint (gnomAD): Loss-of-function variants: 10 observed, 12.91 expected, observed/expected ratio (o/e) 0.77, 90% interval 0.48 to 1.31. The upper end of that interval is the gene's LOEUF score, 1.31, which puts it in group 5 of 6, group 1 being the genes least tolerant of losing a copy. Missense variants: 744 observed, 738.42 expected, observed/expected ratio (o/e) 1.01, 90% interval 0.95 to 1.07. Synonymous variants: 262 observed, 262.12 expected, observed/expected ratio (o/e) 1, 90% interval 0.9 to 1.11.
Homologues: Orthologues: chimpanzee ZNF543 (98% identical), macaque ZNF543 (93% identical), rabbit ZNF543 (71% identical). Paralogues in human: ZNF30 (43% identical), ZNF724 (42% identical), ZNF708 (42% identical), ZNF726 (42% identical), ZNF254 (42% identical), ZNF7 (42% identical), ZNF546 (42% identical), ZNF484 (41% identical), ZNF595 (41% identical), ZNF658 (41% identical), ZNF41 (41% identical), ZNF606 (41% identical), and 164 more.
Diseases named in the same sentence as ZNF543 in open-access papers:
ZNF543 is named in the same sentence as 5 diseases in open-access papers, as found by Europe PMC text mining. Sharing a sentence is not in itself a finding about the gene and the disease. The quoted sentences say what the papers report.
colorectal tumors (1 paper, 2024). "For instance, the combined methylation levels of zinc finger protein genes ZNF397OS and ZNF543 could distinguish obesity‐associated colorectal tumors from other colorectal tumors, contributing to precise medical management." (PMID 38405061, 2024).
parkinsonism (1 paper, 2023). Characteristic neurologic anomaly resulting from degeneration of dopamine-generating cells in the substantia nigra, a region of the midbrain, characterized clinically by shaking, rigidity, slowness of movement and difficulty with walking and gait. "The results indicated an increase in TRIM28 gene expression, indicating the association of ZNF543 with TRIM28 in mediating parkinsonism." (PMID 37194005, 2023).
cancer (1 paper, 2023). A tumor composed of atypical neoplastic, often pleomorphic cells that invade other tissues. "The heatmap showed that the 15 CpG sites (located on B3GALNT1, C6orf97, FAM72A, FAM72B, LIFR, OSMR, ZNF264, and ZNF543) well‐distinguished CRC from adjacent normal tissues, WBCs, and 28 other types of cancer in TCGA, as well as 23 other types of cancer in GEO." (PMID 37649326, 2023).
ZNF543 also shares sentences with these, for which no sentence is quoted: colorectal cancer (1 paper); Obesity (1).